TYMSOS (TYMS opposite strand RNA)
Synonyms: formerly C18orf56
Gene: Long non-coding RNA gene on chromosome 18 (630,886 to 658,352, reverse strand). Ensembl gene ENSG00000176912.
Diseases named in the same sentence as TYMSOS in open-access papers:
TYMSOS is named in the same sentence as 9 diseases in open-access papers, as found by Europe PMC text mining. Sharing a sentence is not in itself a finding about the gene and the disease. The quoted sentences say what the papers report.
gastric cancer (4 papers, 2021 to 2024). A primary or metastatic malignant neoplasm involving the stomach. "TYMSOS was upregulated in gastric cancer cells and functioned as a ceRNA to post-transcriptionally regulate gastric cancer progression." (PMID 36227151, 2022). "For instance, TYMSOS through binding the miR-4739 and resulting in the elevated expression of ZNF703 gives rise to the progression of gastric cancer." (PMID 35211508, 2021). "Additionally, in gastric cancer, miR-4739 has been found to play a negative role in TYMSOS, thereby suppressing cell proliferation, migration, and invasion." (PMID 38267862, 2024).
cancer (6 papers, 2021 to 2025). A tumor composed of atypical neoplastic, often pleomorphic cells that invade other tissues. "Previous studies have shown that GSEC and TYMSOS contribute the proliferation and migration of cancer cells." (PMID 36227151, 2022). "Some of the irlncRNAs previously associated with the malignant phenotypes of various cancers, including MIAT, TYMSOS, LINC01063, HOXC-AS1, LINC02454, SCAT1, and LINC01322 were identified in the process of modeling in this study." (PMID 34167440, 2021). "Via performing qRT-PCR, we found that two m6A-related lncRNAs (AC022031.2 and AL590705.3) were upregulated, while seven lncRNAs (TYMSOS, AC026691.1, AL355574.1, AP000873.4, AL390961.2, AC005586.1, and AL139147.1) were downregulated in cancer tissues." (PMID 34399770, 2021). "TYMSOS and NCAPG knockdown inhibited cell proliferation, cell migration, and cancer stem cell self-renewal in A549 cells." (PMID 35211508, 2021).
tumor (3 papers, 2021 to 2023). "As for TYMSOS, there is no report on its relationship with tumor or related mechanism, which therefore requires further study." (PMID 34187591, 2021). "Importantly, we validated these biomarkers using qRT-PCR and found that the gene expression rate of protective factors such as AC093159.1/ TYMSOS, SCAT1 /LINC00460 and Z82243.1/LINC02561 was significantly higher in early versus late tumor stages." (PMID 34167440, 2021).
TYMSOS also shares sentences with these, for which no sentence is quoted: breast carcinoma (2 papers); head and neck squamous cell carcinoma (1); lung adenocarcinoma (1); lung carcinoma (1); non-small cell lung carcinoma (1); ovarian carcinoma (1).